KCNK6 (potassium two pore domain channel subfamily K member 6)
Description:
K(+) channel that conducts outward rectifying currents at the membranes of the endolysosomal system. Active in lysosomes where it regulates lysosome numbers and size. In macrophages, enables K(+) efflux coupled to ATP-induced NLRP3 inflammasome activation upon bacterial infection. Cooperates with ATP-gated P2RX7 channels to activate NLRP3 inflammasome, with P2RX7 conducting Ca(2+) and Na(+) influx that sets the membrane potential for K(+) efflux (By similarity). [Isoform 2]: Does not display channel activity.
Synonyms: TOSS; TWIK2; K2p6.1; TWIK-2; KCNK8
Tractability: Small molecule: it belongs to a druggable protein family. Antibody: its Gene Ontology location is reachable by antibodies, with high confidence; UniProt predicts a signal peptide or a membrane-spanning region; the Human Protein Atlas places it where antibodies can reach.
Gene: Protein-coding gene on chromosome 19 (38,319,845 to 38,332,076, forward strand). Ensembl gene ENSG00000099337.
Subcellular location: Late endosome membrane; Lysosome membrane
Subcellular location (Human Protein Atlas): Cytosol; Plasma membrane; Actin filaments
Pathways (Reactome):
Muscle contraction: Phase 4 - resting membrane potential
Neuronal System: Tandem of pore domain in a weak inwardly rectifying K+ channels (TWIK)
Gene Ontology:
Molecular function: potassium channel activity; inward rectifier potassium channel activity; potassium ion leak channel activity
Biological process: positive regulation of NLRP3 inflammasome complex assembly; potassium ion transport; regulation of lysosome size; potassium ion transmembrane transport
Cellular component: late endosome membrane; lysosomal membrane; plasma membrane; voltage-gated potassium channel complex; membrane
Genetic constraint (gnomAD): Loss-of-function variants: 20 observed, 18.88 expected, observed/expected ratio (o/e) 1.06, 90% interval 0.74 to 1.54. The upper end of that interval is the gene's LOEUF score, 1.54, which puts it in group 6 of 6, group 1 being the genes least tolerant of losing a copy. Missense variants: 415 observed, 378.12 expected, observed/expected ratio (o/e) 1.1, 90% interval 1.01 to 1.19. Synonymous variants: 210 observed, 188.67 expected, observed/expected ratio (o/e) 1.11, 90% interval 0.99 to 1.25.
Homologues: Orthologues: chimpanzee KCNK6 (99% identical), macaque KCNK6 (96% identical), pig KCNK6 (88% identical), dog KCNK6 (86% identical), mouse Kcnk6 (85% identical), guinea pig KCNK6 (84% identical), zebrafish kcnk6 (51% identical), tropical clawed frog kcnk6 (49% identical), Caenorhabditis elegans twk-46 (31% identical), Caenorhabditis elegans twk-22 (24% identical), Drosophila melanogaster Ork1 (24% identical), Caenorhabditis elegans twk-45 (23% identical), and 9 more. Paralogues in human: KCNK1 (42% identical), KCNK7 (32% identical), KCNK2 (28% identical), KCNK16 (28% identical), KCNK4 (28% identical), KCNK10 (28% identical), KCNK17 (28% identical), KCNK15 (26% identical), KCNK3 (26% identical), KCNK9 (25% identical), KCNK12 (23% identical), KCNK13 (23% identical), and 2 more.
Diseases named in the same sentence as KCNK6 in open-access papers:
KCNK6 is named in the same sentence as 24 diseases in open-access papers, as found by Europe PMC text mining. Sharing a sentence is not in itself a finding about the gene and the disease. The quoted sentences say what the papers report.
breast carcinoma (9 papers, 2013 to 2025). "Through analysis of TCGA data, it was found that the upregulation of KCNK6 is associated with malignant progression of breast cancer." (PMID 34195184, 2021). "KCNK6 is as an overexpressed gene that promotes breast cancer cell proliferation, invasion, and migration." (PMID 37234983, 2023). "KCNK6 (Potassium channel subfamily K member 6) promotes breast cancer cell proliferation and metastasis." (PMID 38203246, 2023). "KCNK6 is upregulated in thyroid carcinoma and breast cancer and is related to the proliferation, invasion, and migration of breast tumor cells." (PMID 35847579, 2022). "We found that the expression of potassium channel protein KCNK6 in normal breast tissue was significantly lower than that in breast cancer tissue (P < 0.05)." (PMID 34195184, 2021). "Although it has been reported that KCNK6 expression is increased in breast cancer and thyroid carcinoma, its function had not been previously reported." (PMID 34195184, 2021). "We, therefore, sought to verify the expression of KCNK6 in breast cancer and detect its function in the malignant phenotype to explore its potential as a new therapeutic target for breast cancer." (PMID 34195184, 2021). "Although KCNK6 is reportedly overexpressed in breast cancer cells, its role in malignant progression of tumors, has not been reported." (PMID 34195184, 2021). "We then detected the expression of KCNK6 expression in clinical breast cancer samples via immunohistochemistry." (PMID 34195184, 2021). "Further, we found that high levels of KCNK6 decrease the adhesion and hardness of breast cancer cells, while its knockdown increased these properties, thereby affecting their biophysical phenotypes." (PMID 34195184, 2021). "In this study, through the data mining of two groups of breast cancer gene expression profile microarray datasets, we found that the potassium channel protein KCNK6 was expressed at an abnormally high level in breast cancer cells." (PMID 34195184, 2021). "Through data mining of the microchip dataset, we found that the expression of KCNK6 was significantly increased in breast cancer." (PMID 34195184, 2021). "The results showed that the expression level of KCNK6 was significantly higher in breast cancer tissues than in normal breast tissues (P < 0.0001)." (PMID 34195184, 2021). "Compared with normal breast tissues, the expression of KCNK6 was significantly upregulated in breast cancer tissue (∗∗∗P < 0.001)." (PMID 34195184, 2021). "KCNK6 expression is increased in breast cancer, and its correlation with clinical progression and breast cancer prognosis is worthy of further study." (PMID 34195184, 2021). "Clinical patient information KCNK6 expression in breast cancer tissues and corresponding adjacent tissues of paraffin-embedded tissue sections." (PMID 34195184, 2021). "The role of KCNK6 in cancer is not well understood, but under-expression of KCNK6 and KCNK15 was associated with the triple-negative subtype of breast cancer." (PMID 34281234, 2021). "This suggests that more detailed analysis of KCNK6 will help to clarify the pathogenesis of breast cancer, identify new therapeutic targets for breast cancer, and promote development of new tumor therapy strategies." (PMID 34195184, 2021). "Moreover, KCNK6 overexpression enhances cell proliferation, invasion, and migration in a breast cancer cell line model." (PMID 40427758, 2025). "Additionally, KCNK6 has been reported to be overexpressed in both breast cancer and thyroid carcinoma." (PMID 40869089, 2025). "The same study found that KCNK6 was overexpressed in a clinical cohort of breast cancer." (PMID 40427758, 2025). "Moreover, overexpressed KCNK6 was found to enhance the proliferation, invasion, and migration ability of breast cancer cells." (PMID 34195184, 2021).
breast carcinoma (continued). "We further verified, via immunohistochemistry, that KCNK6 expression is significantly upregulated in breast cancer and may lead to enhanced proliferation and invasion in breast cancer cell lines." (PMID 34195184, 2021). "Hence, the results of this study provide a theoretical basis for KCNK6 to become a potential molecular target for breast cancer treatment in the future." (PMID 34195184, 2021). "Taken together, these results suggest that KCNK6 may affect a series of physiological activities in breast cancer cells, including cell invasion and metastasis, by altering their biophysical characteristics." (PMID 34195184, 2021). "We have reason to believe that through more in-depth and detailed investigations, KCNK6 may become a new biomarker of breast cancer." (PMID 34195184, 2021). "It is, therefore, suggested that the development of specific small molecular therapeutic drugs for targeting KCNK6 may offer potential for treating diseases, including breast cancer." (PMID 34195184, 2021). "We further verified that KCNK6 expression is upregulated in breast cancer biopsies." (PMID 34195184, 2021). "We further detected the biological function of KCNK6 in breast cancer cell lines and found that overexpression of KCNK6 could significantly enhance the proliferative, invasion, and migratory properties of MDA-MB-231 and MCF-7 cells." (PMID 34195184, 2021). "We further designed experiments to verify whether the expression level of KCNK6 affects breast cancer cell invasion and migration." (PMID 34195184, 2021). "Additionally, in the collected clinical tissue samples, we found that KCNK6 expression was significantly higher in breast cancer tissue than in normal breast tissue." (PMID 34195184, 2021). "Moreover, we observed that the proliferative, invasive, and migratory capacity of breast cancer cells with KCNK6 knocked down was significantly weakened." (PMID 34195184, 2021). "Simultaneously, we observed via transwell cell invasion assay results, that overexpression of KCNK6 also promotes the invasive ability of breast cancer cell lines compared to control cells; whereas the opposite effect was observed following KCNK6 knockdown (∗∗∗P < 0.001; ****P < 0.0001)." (PMID 34195184, 2021). "In short, we found that the potassium channel protein KCNK6 is significantly overexpressed in breast cancer and that its expression level significantly affects the proliferation, invasion and migration capacity of breast cancer cells, accompanied by changes in their biophysical characteristics." (PMID 34195184, 2021). "Our study confirmed, for the first time, that increased KCNK6 expression in breast cancer cells may promote their proliferation, invasion, and migration." (PMID 34195184, 2021). "The high expression of the potassium channel protein KCNK6 in breast cancer suggests that it may be involved in the malignant transformation of breast cancer." (PMID 34195184, 2021). "Therefore, we designed experiments to explore whether the expression of KCNK6 affects breast cancer cell proliferation." (PMID 34195184, 2021). "Moreover, considering that ion channels serve as therapeutic targets for many small molecular drugs in clinical treatment, targeting KCNK6 may represent a novel strategy for breast cancer therapies." (PMID 34195184, 2021). "Thus, KCNK6 may participate in regulating proliferation, invasion, and migration in breast cancer cells." (PMID 34195184, 2021). "Here, we found that potassium channel subfamily K member 6 (KCNK6) is significantly overexpressed in breast cancer, however, its function in tumors has not been reported." (PMID 34195184, 2021).
Sepsis (4 papers, 2021 to 2023). Sepsis is defined as life-threatening organ dysfunction caused by a dysregulated host response to infection. "Deletion of the Kcnk6 gene (encoding TWIK2) suppressed NLRP3 activation in macrophages and suppressed sepsis-induced lung inflammation." (PMID 36378463, 2023).
pulmonary hypertension (3 papers, 2016 to 2021). Increased pressure within the pulmonary circulation due to lung or heart disorder. "KCNK6 is also highly expressed in the vascular system, when its abnormally low expression may lead to vascular dysfunction and pulmonary hypertension." (PMID 34195184, 2021).
thyroid cancer (3 papers, 2020 to 2022). "However, KCNK1, KCNK6, KCNK7, KCNK9, KCNK10, KCNK13 and KCNK16 mRNA expressions were not related to the prognosis of patients with thyroid cancer." (PMID 32742463, 2020).
epilepsy (1 paper, 2021). A brain disorder characterized by episodes of abnormally increased neuronal discharge resulting in transient episodes of sensory or motor neurological dysfunction, or psychic dysfunction. "Additionally, a number of VGKCs including KCNB2, KCNF1, KCNK6, KCNK9 and KCNJ5 are significantly upregulated in the NRXN1α+/- transcriptome, and gain of function of VGKCs has been identified in neurodevelopmental disorders including epilepsy." (PMID 34525970, 2021).
Hypertension (1 paper, 2023). The presence of chronic increased pressure in the systemic arterial system. "A member of this gene family, KCNK6 is known to contribute to hypertension." (PMID 37274792, 2023).
lung carcinoma (1 paper, 2025). "Lung cancer studies included E3 (KCNK1), E8 (KCNK1, KCNN4), E12 (KCNH8, KCNMB2), E23 (KCNU1), E30 (KCNQ5-IT1), E35 (KCNK1), E43 (KCNK6), E49 (KCNN4), 2), E54 (KCNJ13), E63 (KCNK12), and E67 (KCNMB2)." (PMID 40867621, 2025).
tumor (4 papers, 2017 to 2025). "KCNK6 and KCNK15 overexpression (associated in our study with luminal-A subtype) also appeared to be associated with tumor sample-type (both p < 2.2 × 10−16)." (PMID 28899398, 2017). "Moreover, a total of 7 KCNKs were found to be closely related to the tumor stage, which were KCNK1, KCNK2, KCNK5, KCNK6, KCNK7, KCNK19, and KCNK15." (PMID 32742463, 2020).
cancer (3 papers, 2021 to 2023). A tumor composed of atypical neoplastic, often pleomorphic cells that invade other tissues.
KCNK6 also shares sentences with these, for which no sentence is quoted: asthma (1 paper); autoimmune disease (1); Birk-Barel syndrome (1); bladder tumors (1); breast tumor (1); developmental delay (1); endometrial cancer (1); endotoxemia (1); Intellectual disability (1); lung injury (1); migraine (1); neurodevelopmental disorder (1); papillary thyroid carcinoma (1); Stroke (1); urothelial carcinoma (1).